PHETA1 (PH domain containing endocytic trafficking adaptor 1)
Description:
Plays a role in endocytic trafficking. Required for receptor recycling from endosomes, both to the trans-Golgi network and the plasma membrane.
Synonyms: Ses1; IPIP27A; FAM109A; FLJ32356
Tractability: No criterion of Open Targets' tractability assessment is met for any kind of drug.
Gene: Protein-coding gene on chromosome 12 (111,360,651 to 111,369,173, reverse strand). Ensembl gene ENSG00000198324.
Subcellular location: Early endosome; Recycling endosome; Golgi apparatus, trans-Golgi network; Cytoplasmic vesicle, clathrin-coated vesicle
Gene Ontology:
Molecular function: protein binding; protein homodimerization activity
Biological process: endosome organization; receptor recycling; retrograde transport, endosome to Golgi
Cellular component: clathrin-coated vesicle; early endosome; recycling endosome; trans-Golgi network; cytosol; Golgi apparatus
Genetic constraint (gnomAD): Loss-of-function variants: 3 observed, 1.65 expected, observed/expected ratio (o/e) 1.81, 90% interval 0.62 to 1.94. That is too few expected variants to judge how well the gene tolerates losing a copy. Missense variants: 345 observed, 327.54 expected, observed/expected ratio (o/e) 1.05, 90% interval 0.96 to 1.15. Synonymous variants: 153 observed, 145.92 expected, observed/expected ratio (o/e) 1.05, 90% interval 0.92 to 1.2.
Homologues: Orthologues: chimpanzee PHETA1 (99% identical), dog PHETA1 (71% identical), guinea pig PHETA1 (65% identical), pig PHETA1 (65% identical), rat Pheta1 (61% identical), mouse Pheta1 (61% identical), tropical clawed frog pheta2 (44% identical), tropical clawed frog pheta1 (40% identical), zebrafish pheta2 (33% identical). Paralogues in human: PHETA2 (39% identical), PLEKHJ1 (20% identical).
Diseases named in the same sentence as PHETA1 in open-access papers:
PHETA1 is named in the same sentence as 13 diseases in open-access papers, as found by Europe PMC text mining. Sharing a sentence is not in itself a finding about the gene and the disease. The quoted sentences say what the papers report.
Lowe oculocerebrorenal syndrome (2 papers, 2020 to 2025). "Rare mutations in human PHETA1 lead to Lowe oculocerebrorenal syndrome, which includes pathophysiology in seizures, mental retardation, and structural brain abnormalities." (PMID 40586517, 2025). "Both PHETA1 and PHETA2 have a C-terminal phenylalanine-histidine motif (F&H motif) that serves as a binding site for OCRL, encoded by a gene that is mutated in Lowe syndrome (MIM #309000)." (PMID 32152089, 2020). "Despite the known roles of PHETA1 in facilitating OCRL function, the UDP patient did not present with the typical manifestations of Lowe syndrome, i.e. congenital cataracts, cognitive impairment, and renal tubular and glomerular dysfunction." (PMID 32152089, 2020).
congenital myasthenic syndrome (1 paper, 2021). Congenital myasthenic syndrome (CMS) is a group of genetic disorders of impaired neuromuscular transmission at the motor endplate characterized by fatigable muscle weakness. "For instance, anomalies in PHETA1/2 have been associated with abnormal bone formation resulting in craniofacial defects, HAGH has been associated with skin, bone and joint infections in Yaws disease and mutations in GFPT1 have been associated with muscle weakness in congenital myasthenic syndrome." (PMID 34868271, 2021).
PHETA1 also shares sentences with these, for which no sentence is quoted: cancer (2 papers); bacterial infection (1); colorectal adenoma (1); esophageal carcinoma (1); Hypertension (1); Obesity (1); Renal cyst (1); rheumatoid arthritis (1); scoliosis (1); Stroke (1); type 2 diabetes (1).